CDC45 (cell division cycle 45)
Diseases named in the same sentence as CDC45 in open-access papers (continued):
Sharing a sentence is not in itself a finding about the gene and the disease.
tumor (continued). "Among the clinicopathological features, CDC45 expression was positively related with tumour size (P = 0.034) and microvascular invasion (P = 0.046)." (PMID 33614286, 2021). "A previous study also revealed that the CDC45 protein level is consistently higher in various kinds of human tumour cells than in normal cells so that was identified as a proliferation-associated antigen." (PMID 33614286, 2021). "Circ-CDC45 acted as a sponge and regulated the expression of miR-527 to promote tumor cell growth and invasion." (PMID 35036156, 2021). "This study investigated CDC45 expression in tumour tissues and defined its prognostic value in HCC patients." (PMID 33614286, 2021). "Further studies investigated the relationship between CDC45 and tumor-infiltrating immune cells via CIBERSORT." (PMID 34557356, 2021). "In the present study, we examined the protein expression level of CDC45 in HCC by comparing tumours with neighbouring normal tissues in tissue microarrays (TMAs)." (PMID 33614286, 2021). "IHC staining was used to evaluate the CDC45 protein expression levels in HCC tumour samples and matched normal tissues from 56 HCC patients." (PMID 33614286, 2021). "In non-small cell lung cancer, CDC45 can promote the growth of tumour cells and was defined as an oncogene." (PMID 33614286, 2021). "Functional enrichment analyses were used to describe significantly involved hallmark pathways of differentially expressed genes (DEGs, which were screened out according to the high or low expression of CDC45 in tumour tissues)." (PMID 33614286, 2021). "Circ-CDC45 was also elevated in GBM and associated with larger tumor size, higher grade, and poor OS in glioma." (PMID 33195421, 2020). "This is in agreement with another study that found Cdc45 to reside at low levels in human tumor cells." (PMID 21390258, 2011). "In addition, we analyzed and concluded that CDC45 was closely related to the tumor microenvironment, immune cell infiltration, and immune checkpoint." (PMID 37642814, 2024). "Altogether, these findings imply that CDC45 plays a crucial role in the regulation of muscle development and function, which may affect the tumor cell invasion and metastasis mechanism of GC." (PMID 38515458, 2024). "Meanwhile, we could see that CDC45 expression had a significant increase in tumor tissues than in normal tissues (p < 0.05)." (PMID 37642814, 2024). "CDC45 transcription is correlated with carcinogenesis and is valuable for tumor prognosis." (PMID 38485838, 2024). "CDC25C and CDC45 are closely related to tumor development and tumorigenesis." (PMID 38725628, 2024). "Further analysis revealed a negative correlation between CDC45 and cell cycle-related proteins, stemness-related markers, and tumor mutations." (PMID 38589907, 2024). "Mouse experiments confirmed that CDC45 knockdown inhibited tumor growth." (PMID 38589907, 2024). "To further clarify the mechanisms underlying the enhancement of cell proliferation, migration, and invasion by high CDC45 expression, we analyzed the protein expression of EMT markers closely associated with tumor metastasis in A549 and H1299 cells by WB analysis." (PMID 38589907, 2024). "By addressing the mechanistic questions surrounding CDC45's role in stemness and cell cycle regulation, we may potentially refine treatment approaches to more effectively suppress tumor cell proliferation and metastasis." (PMID 38589907, 2024). "Additionally, the effectiveness of CDC45 in differentiating between early tumor pathology (stage I and II) and normal controls was confirmed through ROC analysis." (PMID 38515458, 2024). "Specifically, the inhibition of DBF4, CCNA2, CCNB1, MCM6, CDC45, CHEK1, and CDC6 may be implicated in KCNQ1-mediated tumor suppression." (PMID 35216393, 2022). "However, in our study, we found that CDC45 expression at the protein level was downregulated in HCC by detecting the expression of CDC45 in tumour tissues and matched adjacent normal liver tissues from 56 HCC patients." (PMID 33614286, 2021).
tumor (continued). "We used immunohistochemistry (IHC) staining to examine the expression of CDC45 in tumour tissue specimens and compare them with adjacent normal tissue specimens using a constructed tissue microarray (TMA) and analyzed how clinical features are related to HCC prognosis." (PMID 33614286, 2021). "Moreover, it was demonstrated that the upregulation of CDC45 in papillary thyroid cancer is correlated with a more advanced tumour stage." (PMID 33614286, 2021). "Circ-CDC45 serves as a sponge for miR-516b and miR-527 which functions as tumor-suppressor in GBM." (PMID 33195421, 2020). "Therefore, the knockdown of CDC45 inhibited subcutaneous tumor growth in mice." (PMID 38589907, 2024). "However, the role of CDC45 in tumor stemness and lymph node metastasis has been rarely reported." (PMID 38589907, 2024). "We further investigated the expression of CDC45 in tumors at different stages and found that in all 28 studied tumors, CDC45 was highly expressed in most tumors compared to normal controls, and its expression level gradually increased with progressive tumor stage." (PMID 35677427, 2022). "Moreover, our results demonstrated that high protein expression of CDC45 negatively correlated with tumour size and metastasis, which revealed that decreased expression of CDC45 may promote cancer progression." (PMID 33614286, 2021). "TOPBP1 and CDC45 play an important role in DNA replication, and MTBP plays a critical role in promoting the growth and migration of tumor cells." (PMID 37266876, 2024). "Next, using machine learning, we identified and validated three hub genes (CDC45, CDC20, TPX2), with CDC20 showing the highest correlation with tumor stemness and limited previous research." (PMID 39114311, 2024). "As resident tumor macrophages expressing MKI67, CDK1, and CDC45, HMGB1, and others, Prolif-TAMs were likely pro-inflammatory, profibrotic, and promoting tumor progression." (PMID 39184073, 2024). "The results revealed that in tumor tissues from ccRCC patients, POLQ expression positively correlated with the expression of CDC6, CDC45, CDT1, FANCD2, and MCM2." (PMID 38270643, 2024). "This is based on ample evidence that replication stress can induce CIN and our observation that replication factors are over-expressed in tumours with high levels of W-CIN and that over-expression of the replication genes GINS1 and CDC45 can induce W-CIN." (PMID 35326573, 2022). "In vivo studies, PIF1 was related to the essential replication initiation cofactor CDC45, and the interaction of endogenous CDC45 and C-terminal-FLAG-tagged PIF1 in human tumor cells was confirmed by coimmunoprecipitation." (PMID 36685888, 2022). "Meanwhile, MCM7 and CDC45, which were involved in this process, were correlated with MCM3 and differentially expressed between normal and tumor tissues." (PMID 36133906, 2022). "Results showed that four of these hub proteins (AURKA, CDC45, ESPL1, and RAD54L) were over-expressed in all tumor subtypes." (PMID 32932728, 2020). "Meanwhile, we found that CDC45 was correlated with tumor mutational burden (TMB) and microsatellite instability (MSI) but not tumor neoantigen burden (TNB)." (PMID 37642814, 2024). "Additionally, we assessed the correlation between CDC45, CDC20, and TPX2 with tumor stemness using Pearson correlation analysis." (PMID 39114311, 2024). "However, the correlation of CDC45 expression with PFS and OS of cancer patients was different at different tumor stage." (PMID 34143800, 2021). "Compared with other genes, MCM2, TOP2A, CDC45, KNTC1, RFC4 and RMI2 were highly expressed in CESC tumor tissues and might be better indicators of prognosis." (PMID 34174849, 2021). "RRM2 showed no expression in both normal and tumor tissues, while CDC45, and CDC6 were mainly expressed in tumor cells and immune cells." (PMID 32969465, 2020).
tumor (continued). "Decreased survival was observed in Kaplan Meier survival curves for cases with MCM 2, 4, and 5, CDC45, GINS1, and MCM10 expression above the tumor cohort average, in agreement with the general concept that high expression of proliferation genes correlates with decreased survival." (PMID 31857847, 2019). "The ANOVA F test revealed that there was no statistically significant overall correlation of CDC45 mRNA expression with tumor size (p = 0.085) or histological grade (p = 0.887)." (PMID 19116018, 2008). "We hypothesize that miRNAs that show significant up- or downregulation in GPs may regulate the expression of genes that are involved in the cell cycle (AURKB, CDC45, and CDK6), cell proliferation (EGFR and VEGFA), and angiogenesis (VEGFA) that support tumor growth." (PMID 40143207, 2025). "Interestingly, five genes (CDC45, KIF13B, ORC6, SHCBP1,and CAPN8) were not present in previously reported molecular tumor grading signatures." (PMID 26474389, 2015).
cancer (46 papers, 2008 to 2025). A tumor composed of atypical neoplastic, often pleomorphic cells that invade other tissues. "For instance, CDC45 is associated with DNA methylation in a variety of cancers and its expression is negatively correlated with overall survival of GBM." (PMID 39315277, 2024). "CDC45, a proliferation‐associated antigen, is up‐regulated in human cancer cell lines promoting cancer cell division." (PMID 35810383, 2022). "Numerous evidences have shown that CDC45 is required during the process of DNA replication, and CDC45 overexpression is also associated with cancer cell proliferation." (PMID 33061942, 2020). "The previous studies reported that CDC45 may be a proliferation-associated antigen and contribute to the progression of malignant tumors." (PMID 34557356, 2021). "Thus, except for MCMs, GINS and Cdc45 could also serve as diagnostic and prognostic biomarkers for multiple tumors, which also as a druggable target to treat cancers." (PMID 36776764, 2023). "Initially, the expression of CDC45 was investigated across various cancer types using RNA-seq data from TCGA." (PMID 38515458, 2024). "A previous study also showed that the level of CDC45 protein is steadily higher in several types of human cancer cells than in primary human cells and was detected as a proliferation-associated antigen." (PMID 38485838, 2024). "According to some other studies, CDC45 is upregulated in some cancers, which led to the assumption that it is a leukemogenic gene." (PMID 38485838, 2024). "CDC45, a key protein involved in the initiation of DNA replication, is upregulated in many cancers, and its expression is significantly negatively correlated with patient prognosis." (PMID 37920207, 2023). "In tongue squamous cell carcinomas (SCC), higher expression of Cdc45 with severe lymph node status is observed in malignant tumor than mild precancerous epithelial dysplasia, which implies its role in distinguish precancerous dysplasia from SCC." (PMID 36776764, 2023). "Previous researches and out study indicate that the role of CDC45 involved in cancer progression required further studies to confirm." (PMID 34143800, 2021). "Previous studies have shown high CDC45 expression in human cancer-derived cell lines, including breast carcinoma, cervix carcinoma and acute lymphoblastic leukaemia." (PMID 33614286, 2021). "In most studies, CDC45 was reported over-expression and enrichment in pathways such as cell cycle arrest in several cancers." (PMID 34143800, 2021). "The genes (CDC45, ESPL1 and RAD54L) in our prognostic model have been previously reported to be associated with various cancers." (PMID 32425694, 2020). "It is required for DNA synthesis during genome duplication, as a component of the Cdc45-MCM-GINS (CMG) helicase and implicated in diverse human cancers including BC." (PMID 32932728, 2020). "A CDK-independent function of Chk1 in regulation of CDC45 loading was first described in cancer cells exposed to the carcinogen benzo[a]pyrene dihydrodiol epoxide." (PMID 28030798, 2017). "Consistent with the antiproliferative effect of metformin in cancer cells, our data shows a decreased expression in many cell cycle kinases such as CDKs, CDC45, and CDC25C." (PMID 29085821, 2017). "In support of this, reciprocal immunoprecipitation of C-terminal-FLAG-tagged PIF1 and endogenous CDC45 in human cancer cells has been reported, suggesting that PIF1 associates with the essential replication initiation co-factor CDC45 in vivo." (PMID 25359767, 2014). "CDC45 protein has been shown to be overexpressed in various human cancer cell lines, including MCF-7." (PMID 23320178, 2012). "CDC45 overexpression has been reported in many different cancer types, but few studies have examined changes in CDC45 expression in the premalignant stage." (PMID 19116018, 2008).
cancer (continued). "In cancer therapy, downregulation of CDC45 might be a positive indicator of successful anticancer effects that change the cell status from proliferative to non-proliferative, further enhancing the apoptosis pathway following S-phase arrest." (PMID 37921901, 2024). "CDC45 knockdown promotes S-phase arrest and induction of apoptosis in human cancer cells." (PMID 37921901, 2024). "Except for MCMs, concurrent overexpression of GINS and Cdc45 are also observed in various cancers." (PMID 36776764, 2023). "Two previous studies have found that CDC45 could promote some cancers by co-expressing with other genes." (PMID 36226184, 2022). "It is possible that besides being a key component during DNA unwinding, CDC45 functions as a cell cycle regulator, which might be a potential therapeutic target for cancer disease." (PMID 35642733, 2022). "Knockdown of TOP2A and CDC45 has been shown to suppress the growth of various cancer cells." (PMID 36142506, 2022). "In addition, to explore the detailed mechanism between CDC45 and carcinogenesis as well as reveal the mechanism of CDC45 in other cancers." (PMID 33614286, 2021). "In conclusion, our results provide evidence that candidate pathogenic genes such as MMP1, CDC45, and CAT and their enriched pathways, respectively, of pathway in cancer, cell cycle, and methane metabolism might be involved in the pathogenesis of CC." (PMID 27034707, 2016). "Although the frequent occurrence of CDC45 overexpression in malignant tumors and its established correlation with poor overall survival has been systematically elucidated in pan-cancers, further systematic research of CDC45 molecular biological function and clinical application in GC are warranted." (PMID 38515458, 2024). "Therefore, high expression of CDC45 induced DNA stress of cancer cells, leading to cell death might explain the poor prognosis of low CDC45 expression in HCC patients." (PMID 33614286, 2021). "Among the genes closely related to SPSB2 expression, CDC45, RAD51, TRIP13, MYBL2, and CDC20 play essential roles in cancer development." (PMID 40149497, 2025). "CDC45 plays a significant role in the replicative helicase holoenzyme CDC45-MCM-GINS complex and is highly expressed in human cancer-derived cells." (PMID 38725628, 2024). "Literature retrieval showed that the expression of CDCA5 was associated with tumorigenesis and tissue invasion in a variety of cancers, while the results on the roles of ESPL1, CDC45, and ESPL1 in cancers were conflicting." (PMID 34143800, 2021). "Moreover, at the multi-cancer level, known cancer drivers such as CDC45 and NUF2 were identified to be involved in edgetic gains while NTRK1, PRPH and MYOC were determined to be involved in edgetic losses and may serve as targets for widely applicable therapeutic interventions." (PMID 32152446, 2020). "Significantly, candidate genes MMP1, CDC45, and CAT were also, respectively, enriched in the pathway in cancer, cell cycle, and methane metabolism." (PMID 27034707, 2016). "Taken together, these results suggested that a protein network including AURKA, RAD54L, CDC45, and ESPL1 proteins, key molecules of pathways deregulated in cancer, could represent a common regulatory signature to all BC subtypes." (PMID 32932728, 2020). "Since aberrant overexpression of the replication initiation machinery is found in many types of cancers, CDC6, CDT1, MCM2 and CDC45 may also be useful markers for assessing the type and degree of oral pre-malignant as well as malignant lesions." (PMID 19116018, 2008). "By investigating differences in gene expression between the extremes of clinical stages and histological grades, many novel genes have been identified, such as CDC45 and RAD51AP1, and their expression may indicate poor prognosis and play a role in the aggressiveness of the cancer." (PMID 32899298, 2020).
genetic diseases (4 papers, 2021 to 2024). "Mutations in CDC45 can be related to a wide spectrum of genetic disorders." (PMID 38397019, 2024). "The affected fetus was confirmed a compound heterozygote of CDC45 related MGS by whole-exome sequencing, which is critical in identifying rare genetic diseases." (PMID 34000999, 2021).
infection (2 papers, 2020). The state of being infected such as from the introduction of a foreign agent such as serum, vaccine, antigenic substance or organism. "Survival of the cdc45-/-/+ parasites within host macrophages was examined by infecting macrophages with metacyclic parasites, and analyzing the number of intracellular parasites right after the 5 hour infection period as well as 24 hours and 48 hours later." (PMID 32413071, 2020). "Of the top 10 transcripts upregulated at peak HIV-1 viral load, the majority (6 out of 10) were related to cell cycle and cell division including RRM2, MYBL2, CDK1, UBE2C, CDC45, and TK1 with 8 to 15-fold increased expression compared to the pre-infection samples." (PMID 31937782, 2020).
CDC45 also shares sentences with these, for which no sentence is quoted: lung adenocarcinoma (3 papers); squamous cell carcinoma (3); lymphoma (2); microtia (2); acute leukemia (1); cervical squamous cell carcinoma (1); Cirrhosis (1); Coats plus syndrome (1); diffuse large B-cell lymphoma (1); dwarfism (1); dysplasia (1); endocervical adenocarcinoma (1); endometrial carcinoma (1); glioblastoma (1); immune dysfunction (1); liver (1); medulloblastoma (1); metastatic melanoma (1); nasopharyngeal carcinoma (1); neutropenia (1); pancreatic cancer (1); pancreatic insufficiency (1); psoriasis (1); rapadilino syndrome (1); renal carcinoma (1); sarcoma (1); Seckel syndrome (1); stomach cancer (1); thrombosis (1); van den Ende-Gupta syndrome (1).